MED15P4 (mediator complex subunit 15 pseudogene 4)
Gene: Transcribed unprocessed pseudogene on chromosome 2 (131,535,187 to 131,536,988, reverse strand). Ensembl gene ENSG00000224679.
Diseases named in the same sentence as MED15P4 in open-access papers:
MED15P4 is named in the same sentence as 1 disease in open-access papers, as found by Europe PMC text mining. Sharing a sentence is not in itself a finding about the gene and the disease. The quoted sentences say what the papers report.
tumor (1 paper, 2022). "In addition, the transcript of mediator complex subunit 15 pseudogene 4 (MED15P4) showed a strong association with LINC01087 in 3 out of the 5 tumor types (i.e., OV, STAD and TGCT), and a moderate correlation in ESCA." (PMID 36497462, 2022).